CD14 (CD14 molecule)
Diseases named in the same sentence as CD14 in open-access papers (continued):
Sharing a sentence is not in itself a finding about the gene and the disease.
infection (continued). "ApoBrdU Tunel assays further demonstrated a significant decrease of programmed cell death for CD3+, CD14+, and CD19+ PBMCs at 6 hours post-infection with USA300Δhla and USA300ΔsaeR/S relative to USA300." (PMID 22574180, 2012). "Consistent with CD34+ infection, UL123 (IE1) transcript was transiently expressed during latency in infected CD14+ cells." (PMID 23300789, 2012). "FIX-WT, FIX-Rev, and FIX-ΔLUNA infected HF cells or CD14+ cells were fixed at 1 dpi and stained for IE and LUNA proteins to monitor infection and LUNA protein expression." (PMID 23300789, 2012). "Consistent with CD34+ hematopoietic stem cell (HSC) infection, FIX-WT and FIX-Rev infected CD14+ cells expressed UL138 transcripts through 10 dpi." (PMID 23300789, 2012). "Since CD3 CD14 CD19 negativity and CD16 positivity is characteristic for the NK cells, we concluded that the infection with the wild type strain or any mutant of S. Enteritidis with functional SPI-2 resulted in the depletion of NK cells in spleen." (PMID 20226037, 2010). "Decidual CD14+ cells, which are the main decidual targets of HIV-1 R5 infection, are present in similar numbers in the decidua basalis (DB) and in the decidua parietalis (DP)." (PMID 19543402, 2009). "Since the highest percentage of p24+ cells is detected in HIV-1BaL infected CD14+ cells, we can conclude that the CD14+ cells are the main target of HIV-1BaL infection." (PMID 19543402, 2009). "Nevertheless after 48 h of infection TLR2-/-/CD14-/-mice had higher concentrations of bacteria in both CSF and brain than either TLR2-/-or CD14-/-mice." (PMID 17428319, 2007). "At 14 days post-infection, a 94% lower IFU count was recorded for CD14-/- mice (6.3 × 103 +/- 8.9 × 103 IFU) when compared to C57BL/6J mice (1.1 × 105 +/- 1.6 × 105 IFU)." (PMID 16995947, 2006). "Since TLR2 is involved in Chlamydia-induced TGF-beta, an anti-inflammatory cytokine with an important role in fibrosis, and thus very likely in post-infection tubal pathology, it might explain why CD14 polymorphisms may not severely impact the development of tubal pathology." (PMID 16368002, 2005). "Hence, CD14 may play a pivotal role in determining the balance of infection and inflammation in CF." (PMID 15975149, 2005). "Infection of PBLs with WR-TK(-) virus resulted in similar percentages of infected CD14 and CD56/CD16 positive cells, although a slight decrease of infection rates was noted in CD19 cells." (PMID 15555076, 2004). "In contrast, infection with LT2 upregulated MD2, CD14, MyD88, and TRIF mRNA expression." (PMID 41474380, 2026). "CD14 pertains to the classical CD14++CD16− monocyte subpopulation, whereas CD14−CD16+ monocytes are precursors for pro-fibrotic M2 macrophages, which are crucial players in infection, inflammation, and disease pathogenesis." (PMID 40136968, 2025). "CD14 on the membrane of infected PAMs was significantly increased as early as 3 hpi, and it did not continue to rise with prolonged infection time." (PMID 40503879, 2025). "Furthermore, within three days post-infection, monocytes in experimental CHIKV infection models in cynomolgus monkeys exhibit increased expression of CD14 and CD16, suggesting that these cells were activated." (PMID 41012652, 2025). "Our results from the present study indicated that, during the acute phase of infection, intermediate (CD14+CD16+) and non-classical (CD14+CD16++) monocytes exhibited increased TLR7 expression." (PMID 41012652, 2025). "Infection of C20 human microglial cells with CHIKV led to significant apoptosis and altered the expression of cell surface markers, including a notable decrease in CD14 and upregulation of HLA-DR expression." (PMID 41012652, 2025). "In the smaller 2021 Cohort, where we had paired pre-infection and infection samples from the same individuals, we replicated the findings of significant enrichment of the orexin receptor pathway' in CD14+CD16− monocytes and NK cells but not in DCs." (PMID 40532694, 2025).
infection (continued). "Our results reveal a distinct biphasic pattern in EV dynamics over the course of infection, characterized by a reduction in EV release from CD4+ T cells and CD14+ monocytes during the active phase, followed by a significant resurgence during and after antimonial therapy." (PMID 40872281, 2025). "Monocytes are known to replenish macrophages in tissues during inflammation and infection, and monocyte derived macrophages (mo-macrophages) within the porcine lung have been previously defined as SLAII++CD11b+CD14+CD163intCADM1lo cells, which appears to consist of CADMlo and CADM− cells." (PMID 41510007, 2025). "We monitored the impact of infection on classical (CD14++CD16–); intermediate (CD14+CD16+); and nonclassical (CD14dimCD16+) monocytes." (PMID 40662355, 2025). "As a surrogate of SARS-CoV-2 antigen after infection, we used peptides covering the immunodominant sequence domains of the SARS-CoV-2 Spike (Peptivator peptide pool [Miltenyi]) to stimulate CD14-depleted PBMCs and measure IFNγ+ and CD107a+ frequencies in both CD4+ and CD8+ primary T cells." (PMID 40503889, 2025). "Of the many proteins reported to be elevated early on in COVID-19 infection and that we tested, only CD14 delineated individuals with Cov from nLongC, while IL-1β decreased over time in Cov but not nLongC many months to years post infection." (PMID 41369364, 2025). "In brief, CAR T cell manufacturing included depletion of CD14+ and CD25+ cells, CD3/28 bead stimulation, transduction with lentivirus at multiplicity of infection of 0.3, removal of beads at day 7–9, followed by expansion for a total of 12–17 days in interleukin (IL)-2 and IL-15 cytokines." (PMID 38867077, 2024). "Monocytes also exhibit prolonged activation in long COVID, with higher frequencies of intermediate (CD14+ CD16+) and non-classical (CD14− CD16+) monocytes observed up to 15 months post-infection." (PMID 40276305, 2024). "The first colonies arose from CD14-negative cells 8 days after infection, and 12 iPSC clones were raised." (PMID 38891103, 2024). "Moreover, several publications have demonstrated that CD14, TLR4, and MD2 gene expression decreases when the inflammatory response to LPS infection is inhibited." (PMID 38785798, 2024). "When PBC patients were exposed to LPS due to infection, LPS could bind to cell surface receptors (such as TLR 4/CD14) and induced the secretion of pro-inflammatory cytokines (such as TNF-α, IL-1, IL-6, IL-8), promoting inflammation." (PMID 38111586, 2023). "TLR4 coreceptor CD14 mRNA expression faithfully copied TLR4 mRNA expression and showed upregulated expression after infection with Salmonella without any influence of previous association with commensal bacteria." (PMID 38003758, 2023). "As the CD14+ PMN subset was enriched at the recovery stage of infection, it may contribute to the resolution of infection by secreting anti-inflammatory cytokines and inducing apoptosis, which is then phagocytosed by macrophages." (PMID 37705063, 2023). "We have previously observed similar results to those shown in this study, displaying an inability for those who develop NI to increase their number of absolute CD14+ monocytes unlike those who recovered without an infection." (PMID 35958579, 2022). "In cells that do not express cell surface CD14, sCD14 can also play the essential role in immune response of cells to LPS, and the level of sCD14 increases during infection and inflammation." (PMID 33886672, 2021). "Western blot analyses revealed that lenti-shHMGB1 infection remarkably decreased HMGB1 expression which resulted in significant upregulation of mRNA level of the macrophage-like differentiation markers (CD14, CD11b, and CSF1R) as compared with the lenti-ctrl infection." (PMID 33128580, 2021). "PVSRIPO infection of healthy donor PBMCs emphasized that the dominant source for cytokine release was CD14+ monocytes, and not T/B cells." (PMID 33767151, 2021).
infection (continued). "SARS‐CoV‐2 may primarily infect monocyte and CD14+ subsets with higher expressions of CCR2 and CX3CR1 which may differentiate and migrate from the periphery to the target sites as macrophages during infection." (PMID 34363351, 2021). "An inverse correlation with infection was observed for the percentage and absolute counts of myeloid dendritic cells and plasmacytoid dendritic cells, MFI of CD14 on CD14+β7-CD16+ monocytes and expression of HLA-DR on CD14+CD91low monocytes." (PMID 34645893, 2021). "Using YFP labelled macrophage tropic HIV (YFP-NL4–3(AD8)), we observed no infection of CD14+ monocytes in PBMC, indicating that the PBMC derived virus originated in T cells." (PMID 34555123, 2021). "The functions of TLR2 on these monocyte subsets may also be dictated by the differential expression of CD14, CD16, TLR10, CD3620,55–58 and/or other receptors capable of modulating DENV infection and DENV-infection-mediated responses." (PMID 32576819, 2020). "Importantly, we defined a population of myeloid cells, primarily CD11cHi monocyte-derived cells, which expressed high levels of CD14, CD38, and Abca1, and had the highest infection rates and bacterial loads." (PMID 32544188, 2020). "However, CD14 and CD38 single positive cells were also in the parenchyma; thus, location cannot account for the high infection rate of CD14+CD38+ cells." (PMID 32544188, 2020). "Previous studies using CD14 knockout mice infected with MTB have shown that these animals have a reduced inflammatory response, which protects them from lethality through the late course of infection." (PMID 32508826, 2020). "The infection of myeloid cells in vitro by Rv.mCherry was independent of CD14 and CD38 expression (middle row)." (PMID 32544188, 2020). "Based on our experimental infection results, we next tested whether CD74 expression on CD14+ monocytes could be used as a cell surface marker that will allow enrichment of cells that contain HCMV genomes in healthy seropositive individuals." (PMID 31967545, 2020). "Immune cells were isolated from peripheral blood (PBMCs) and the PP tissue (PP cells) within each intestinal segment at 28 days post-infection to analyze the frequency of T cells (CD4+, CD8+, γδ+), innate lymphoid cells (ILCs; CD335+) and myeloid cells (CD14+ and CD11c+)." (PMID 33329565, 2020). "One was that CD14, CD38, and ABCA1 expression identify macrophages that are prone to infection." (PMID 32544188, 2020). "Infection of monocyte-enriched PBMCs from both seropositive and seronegative individuals with T. gondii led to an increase of CD14+CD16− classical monocytes and a decrease of CD14+CD16+ double positive monocytes." (PMID 31316920, 2019). "At nine weeks post-infection, in peripheral blood of HIV-1 infected NSG-cmah−/− mice, the decreased proportion of CD3+ cells and specifically CD4+CD45RO+ effector memory cells with increased number of monocytes CD14+ were found." (PMID 30616506, 2019). "The expression and CD14 CD16 was not modified after infection with L.braziliensis (data not shown) but it known that the frequency of intermediate (inflammatory) monocytes is higher in CL patients than in HS." (PMID 31119102, 2019). "Though not specific to the in vitro infection, they expressed less CD14 after encountering T. gondii, as compared to seronegative humans." (PMID 31316920, 2019). "Upon PM2.5 exposure, the expression of TNF-α in response to M.tb MOI 1 and 5 infection or stimulation with PPD, PHA and LPS was significantly decreased in CD3+ and CD14+ PBMC compared to CD3+ and CD14+ PBMC infected with M.tb, or stimulated with PPD, PHA or LPS alone (p < 0.05)." (PMID 31731429, 2019). "Infection with T. gondii led to a dramatic expansion of CD14+CD16− classical monocytes (p < 0.001; ANOVA) with a simultaneous strong decrease of CD14+CD16+ intermediate (p < 0.001) and a moderate decrease of CD14dimCD16+ non-classical monocytes (p < 0.01), as compared to non-infected controls." (PMID 31316920, 2019).
infection (continued). "Common polymorphisms in genes encoding key innate immune pattern recognition receptors including TLR2, TLR4, TLR9, CD14, and NOD2 have been associated with the development of infections in some but not all studies." (PMID 30873165, 2019). "Within the total DR+ cells (P2), infection was mainly seen on cells expressing CD14 (d as the uninfected negative control)." (PMID 30710094, 2019). "They found that both strains productively infected CD14 monocytes, but that infection with Asian viruses led to the expansion of non-classical monocytes, resulting in a M2-skewed immunosuppressive phenotype, marked by IL-10 production." (PMID 30072993, 2018). "The authors show that infection with a miR-UL148D mutant virus results in increased ACVR1B protein levels but no changes in latency or reactivation in a CD14+ monocyte infection model." (PMID 30360396, 2018). "The infection rates of DENV2-eGFP (7.53%) and wild-type DENV2 (6.89%) in CD14+ monocytes with 1 μg/ml 4G2 antibody were similar, indicating equivalent infectivity in CD14+ monocytes between the two viruses." (PMID 29547653, 2018). "In agreement with our findings, it has been reported that the proportion of CD14++CD16+ monocytes increases markedly in acute inflammation, and it could be regarded as a predictive marker for infection." (PMID 28659924, 2017). "The survival effect we observe in neutrophils, involving a likely virion–cell surface interaction, is similar to that observed during non-permissive infection of CD14+ and CD34+ cells, where ERK and PI3K signaling were shown to be key." (PMID 28993776, 2017). "In the SHIV-infected macaques, which spontaneously controlled their viral replication several months after the infection, we found that the proliferation of the CD14+ and Lin-CD15+ MDSCs in the bone marrow 11 months post-infection were also significantly lower than those of the uninfected controls." (PMID 28498847, 2017). "As expected, treatment of experimentally latently infected CD14+ monocytes and CD34+ progenitor cells with F49A-FTP led to a reduction in latently infected cells, as measured by decreases in GFP-expressing latent cells after infection with a GFP-tagged HCMV50." (PMID 28148951, 2017). "As observed for all other cells, infection of bovine CD14+ cells with wt BRSV did not induce phosphorylation of p65 and in fact blocked TNF-α-mediated phosphorylation of p65." (PMID 28714847, 2017). "At 48 hours post infection levels of CD14 decreased in all experimental conditions (data not shown)." (PMID 27558873, 2016). "Also a significant change in the expression (MFI) of the phenotypic markers CD14 (up), CD163 (down) and TLR4+ (down) was measured after infection in both groups." (PMID 27606818, 2016). "Flow cytometry panels were designed to characterize CD3+ T-cells, CD14+ monocytic cells, CD19+ B-cells, myeloid dendritic cells (mDC), NK cells, NKT cells and neutrophil populations across different mucosal portals of infection, as well as RBC-lysed whole blood." (PMID 27164006, 2016). "We also assessed the expression of CD80 by CD11c+ DC and CD14+ monocytes but did not observe any significant changes after FMDV A24 Cruzeiro infection." (PMID 27008425, 2016). "Western blot analysis revealed that lenti-shZFP36L1 infection remarkably decreased ZFP36L1 expression which resulted in significant down-regulation of the mRNA levels of the monocyte/macrophage differentiation markers (CD11B, CD14 and CSF1R) as compared with the lenti-control (lenti-ctrl) infection." (PMID 26542173, 2015). "For instance, CD14 was markedly upregulated in SS2 and H1N1-SS2 infection groups." (PMID 25906258, 2015). "Lentiviral particles expressing bovine CD14 shRNA were used to infect HEK 293 cells expressing CD14 at a multiplicity of infection (MOI) of 100, using a non-infected cell line as blank control, the scrambled shRNA as negative control." (PMID 25889660, 2015).
infection (continued). "TFV treatment suppressed the enhancement of the maker expressions by JR-FL infection in a dose-dependent manner without any effect on the maker expression levels in the uninfected CD14-derived osteoclasts." (PMID 25809599, 2015). "RANTES was not increased significantly during infection, but it correlated with the percent of activated CD14+ CD16+ monocytes in circulation at matched time points (p < 0.05)." (PMID 26683323, 2015). "For human CD141+ DCs, infection-induced up-regulation of IFN-β and STAT-1 gene expression was low compared to CD14+ DCs and CD1c+ DCs, which might also reflect the lack of infection of the cells at these time points." (PMID 25474532, 2014). "Increasing concentrations of IFN-β had a significant inhibitory effect on infection in CD14+ DCs, CD1c+ DCs and macrophages but not in LCs." (PMID 25474532, 2014). "We have shown that whereas the proportion of circulating WC1+ γ/δ T-cells and CD14+ monocyte/macrophage cells did not change after PPRV infection of control goats, there was a decrease in the proportion of circulating CD4+ cells 4 days after challenge." (PMID 24568545, 2014). "CD14-neutralizing antibody slightly decreased the level of infection of monocytes by rgRSV224 (data not shown)." (PMID 24303065, 2013). "These transcripts were present even though immediate early mRNAs were not expressed after approximately 14 days post infection of CD14 (+) monocytes." (PMID 23717203, 2013). "Although at present we do not know the significance of wide spread gene expression in CD14 (+) at early time points post infection, a lytic-type infection upon initial infection of primary cells was observed previously for KSHV and EBV." (PMID 23717203, 2013). "In contrast IFN-α production in CD14+ cell-depleted PBMC cultures in the presence of serum did not depend on infection because UV-RSV and live RSV induced equal amounts of IFN-α." (PMID 24303065, 2013). "While MDBK-derived virions barely infected 0.5% of PBMCs at the multiplicity of infection (MOI) of 3, according to titers measured on MDBK cells, BoMac-derived virions infected these cells substantially more efficiently as around 5% of CD14+ PBMCs became positive." (PMID 24204281, 2013). "Undifferentiated CD14 (+) monocytes were infected with the FIX BAC clinical isolate virus strain and viral immediate early (IE1/IE2), LUNA and UL138 transcript levels were measured at various days post infection using qPCR." (PMID 23717203, 2013). "Furthermore, only animals succumbing to bacterial infection displayed a significant (p < 0.01) increase in both CD14 and TLR expression levels when comparing pre-infection (day 0) versus the time of bacterial challenge on 4 day post-BHV-1 infection." (PMID 22435642, 2012). "Quantitative RT-PCR analysis revealed significantly (p < 0.05) increased CD14 and TLR4 expression in PBMC isolated from WMS calves but only TLR4 expression was significantly (p < 0.05) increased in PBMC from PA calves on day 4 post-BHV-1 infection." (PMID 22435642, 2012). "Finally, a kinetic study was performed on BM aspirated from DV infected rhesus monkeys collected at various time points after infection and stained for CD41, CD61, CD14 and DV antigen." (PMID 23300812, 2012). "CD14 expression level (ΔCt expressed as mean ± 1 SD; n = 10) in PMNs prior to BHV-1 infection (Day 0) were 5.8 ± 0.4 (WMS) and 5.1 ± 0.9 (PA) and CD14 expression levels also remain unchanged during BHV-1 infection (Day 4) at 6.1 ± 0.6 (WMS) and 6.2 ± 0.5 (PA)." (PMID 22435642, 2012). "On the other hand, infection of CD14+ cells with FIX-WT, FIX-ΔLUNA, or FIX-Rev viruses showed no infectious viral particles being released." (PMID 23300789, 2012). "Although we did observe a decreased percentage of CD14 positive cells and consequently an increased percentage of CD14 dim cells 8 h after infection, this was not statistically significant." (PMID 22238612, 2012).